KIT (KIT proto-oncogene, receptor tyrosine kinase)
Diseases named in the same sentence as KIT in open-access papers (continued):
Sharing a sentence is not in itself a finding about the gene and the disease.
mucosal melanoma (continued). "KIT mutations were found in approximately 15% of acral and mucosal melanomas, and BRAF or NRAS mutation was found in approximately 10–15% of acral melanoma, but was less frequent in mucosal melanoma [8•, 9]." (PMID 30675668, 2019). "On the contrary, the co-mutation of NF1 and KIT has not been demonstrated in CjM, while it has been detected in up to 32% of mucosal melanoma." (PMID 31683701, 2019). "Because mucosal melanoma of the head and neck is a rare condition, the frequency of KIT mutations has not been characterized in these tumors." (PMID 29796159, 2018). "However, in patients with KIT-mutated metastatic mucosal melanoma, agents targeting c-KIT failed to provide durable responses." (PMID 34149718, 2021). "CKIT mutations are reported in 21% of mucosal melanoma, and only patients with mucosal melanoma harboring a special subset of CKIT mutations such as L576P and K642E in exon 11 and 13 may have a clinical benefit from c-KIT inhibitors." (PMID 25030020, 2014). "At present, some studies have found that mutations that activate SF3B1 and KIT, the deletion of CDKN2A, PTEN, or SPRED1, and the amplification of CDK4, TERT, KIT, MDM2, or CCND1 are common in mucosal melanoma." (PMID 38065883, 2023). "Conversely, KIT mutations, which are characteristic of ALM and mucosal melanomas, are not present in all tumors arising at acral sites." (PMID 40984902, 2025). "When the mucosal melanoma is triple (BRAF, NRAS, NF1)-negative, KIT is the most commonly mutated gene in vulvovaginal melanomas, while APC and KRAS are detected mainly in sinonasal and anorectal melanomas, respectively." (PMID 34571863, 2021). "A single exception has been recently reported concerning a case of metastatic mucosal melanoma harboring the GNAQQ209P mutation in exon 5, with no mutations of the BRAF, NRAS, or c-KIT genes." (PMID 25695059, 2015). "However, due to the very limited number of KIT activation positive cases, the relation between KIT activation and CT7 and CT10 expression, respectively, in mucosal melanoma is not yet clear and has to be analysed in a larger cohort of patients." (PMID 26161400, 2015).
sarcoma (68 papers, 2006 to 2025). A usually aggressive malignant neoplasm of the soft tissue or bone. "Anyway, molecular techniques have yet revealed that sarcomas were different entities with different biologies and have allowed a better understanding of the pathogenesis of some types of sarcomas (e.g. initiating role of mutation of KIT or PDGFRA receptors)." (PMID 21826194, 2011). "Extensive investigations have confirmed that tumor growth and metastasis depend on angiogenesis, and multiple angiogenic factors such as vascular endothelial growth factor (VEGF), bFGF, TGF-β1, MMP, cyclooxygenase-2 (COX-2), CD34, and c-KIT are associated with the prognosis of sarcoma." (PMID 28969086, 2017). "It was found that sarcomas O-P2, L-P5, and Rm-P6 carry mutations in the CTNNB1 (gene accession number: NG_013302.2), KIT (gene accession number: NG_007456.1), and NF2 (gene accession number: NG_009057.1) genes." (PMID 41300532, 2025). "BK40196 is a dual c-KIT/c-Abl (Abelson) inhibitor but also displays binding affinity to other kinases, including fused in sarcoma (SRC) and FYN." (PMID 40137158, 2025). "Tyrosine kinase inhibitors (TKIs) have become a staple in addressing sarcomas like GIST, where mutations in KIT and PDGFRA genes drive tumorigenesis." (PMID 38228904, 2024). "GIST constitutes the mainstay of theranostic application in sarcoma owing to the highly actionable targets KIT and PDGFRa." (PMID 37998367, 2023). "Exposure of sarcoma cells to [pazopanib + entinostat] caused activation of ERBB1 and c-SRC and in a cell-specific fashion, activations of ERBB2, c-KIT, and c-MET." (PMID 31380285, 2019). "Exposure of sarcoma cells to [pazopanib + entinostat] caused activation of ERBB1, ERBB2, c-KIT, c-MET, and c-SRC." (PMID 31380285, 2019). "Taken together, the results of these 5 sarcoma cases highlight the risk of MCS in children and emphasize the need for KIT sequencing despite the rarity of this disease." (PMID 27602777, 2016). "Cell lines from several sarcoma subtypes with defined molecular backgrounds, such as GIST with KIT mutations and dedifferentiated LPS with MDM2 and CDK4 amplification, were treated with selinexor to investigate potential mechanisms of action." (PMID 26918731, 2016). "Mismatched diagnoses have been suspected in another clinical trial involving rare cancers, the multi-institutional clinical trial regarding imatinib treatment for c-KIT or platelet-derived growth factor receptor (PDGFR)-positive sarcoma." (PMID 25146529, 2015). "All patients had a GIST confirmed by experienced sarcoma pathologists at the four centers, and 52 patients (95%) were characterized by a positive c-KIT expression." (PMID 22703877, 2012). "However, most such attempts, including a phase II clinical trial conducted by the Pediatric Oncology Group (COG) to test the efficacy of imatinib in a variety of pediatric sarcomas with high c-KIT or PDGFR levels, have failed with poor response 13-15." (PMID 38434982, 2024). "A few kinases have been identified as drivers of cell growth in sarcoma cells and four KIs have been approved for the treatment of sarcomas (Imatinib, Pazopanib, Sunitinib and Avapritinib) mostly because on the basis of inhibiting the tyrosine kinases KIT and PDGFR." (PMID 38177929, 2024). "In sarcoma cell lines, the silencing of EWS-Fli1 and PAX3-FOXO1 induces the suppression of cell growth to almost the same level; however, the knockdown of KIT in GIST cells was associated with strong growth suppression (unpublished data)." (PMID 29861864, 2018). "Similarly, objective responses to imatinib have been also reported in 3 children with CM and 1 adult patient with MC sarcoma showing deletion of codon 419 (p.419del) in exon 8 of KIT, a region located within the extracellular domain of the gene." (PMID 28978170, 2017). "Detection of KIT mutation in pre-operative peripheral blood is possible also in numerous other sarcomas, thus it’s not diagnostic." (PMID 26383211, 2015).
sarcoma (continued). "Sarcomas are traditionally classified in two major genetic groups: the first group includes sarcomas with simple karyotypes and specific genetic alterations like EWS-ATF1 fusions in Ewing sarcomas, KIT mutations in GISTs, or PAX3-FKHR fusions in alveolar rhabdomyosarcomas." (PMID 32839432, 2020). "We neither did review of the radiology nor the pathology, but experienced sarcoma radiologists and pathologists at a major reference centre had already confirmed the diagnostic work-up at start of IM, including analyses of KIT and PDGFRA mutations that were found in all patients except three." (PMID 27999655, 2016). "In the PALETTE Phase III trial, Pazopanib targeting VEGFR and both c-KIT and PDGFR receptors improved patient progression-free survival by 3 months and was beneficial in the treatment of resistant metastatic sarcomas." (PMID 37681936, 2023). "Anlotinib (multi-target TKI that inhibits VEGFR, FGFR, PDGFR, KIT, and RET) was evaluated by a multiple-institution retrospective study in 48 patients with advanced sarcomas including 27 OS, eight ES, nine CS, and three chordomas." (PMID 36430263, 2022). "The GIST series (n = 148) was stained for all three markers (TNS2, KIT, and DOG1), while the sarcoma screening series (n = 548) was only stained for TNS2." (PMID 35804982, 2022). "Sorafenib, regorafenib, lenvatinib, and anlotinib, all of which have activity against VEGFR, PDGFR, RET, c-KIT and FGFR, and cabozantinib, which has a different target profile (VEGFR, MET, AXL, and RET), have all shown some clinical benefit in sarcoma." (PMID 34944614, 2021). "Its impressive activity in sarcomas has been primarily shown in GIST, by interrupting the constitutive activation of KIT-mediated signal transduction characteristic of that sarcoma." (PMID 27732970, 2017). "The expression levels of sunitinib targeted-kinases were measured by transcriptome sequencing for PDGFRA/B, KIT, RET, FLT1(VEGFR1), KDR (VEGFR2), and FLT4(VEGFR3) for patient cohort with EMC and other sarcoma histologies." (PMID 28423517, 2017). "A retrospective analysis of patients with relapsed, metastatic, or unresectable sarcomas treated with nivolumab and the multi-RTK inhibitor pazopanib (VEGFR, PDGFR, and KIT) further showed a CBR in two out of the three included osteosarcoma patients, of which one patient had a PR." (PMID 34944614, 2021). "Thirty‐three patients had diagnosis of KIT‐negative GI‐LMS confirmed by sarcoma‐expert pathologist." (PMID 37455549, 2023). "Notably, it has been previously highlighted that high immunohistochemical expression of CD117 (c-kit) can be frequently found in tumours with YWHAE genetic rearrangement, but c-kit-immunoreactive YWHAE-NUTM2A/B sarcomas have not demonstrated known mutations in KIT gene." (PMID 33802452, 2021). "We also note that dramatic therapeutic progress in other sarcomas, particularly in GIST (which are also genomically noncomplex), was achieved with the use of a single, representative, model of oncogenic KIT-dependency." (PMID 36097178, 2022).
leiomyosarcoma (63 papers, 2007 to 2026). An uncommon, aggressive malignant smooth muscle neoplasm, usually occurring in post-menopausal women. "The downregulation of miR-152 in leiomyosarcoma is associated with increased KIT and MET-levels." (PMID 28895916, 2017). "Previously strong diffused expression of KIT was observed in ~75% of leiomyosarcomas, and in 53% of uterine leiomyosarcomas." (PMID 34527573, 2021). "On the other hand, experimental upregulation of miR-152 reduces levels of MET and KIT in leiomyosarcoma cell lines." (PMID 28895916, 2017). "Protein kinase C theta, a downstream effector in the KIT signaling pathway, is used to discriminate between GISTs and leiomyosarcoma or other tumors which have similar histopathology to GISTs." (PMID 22540369, 2012). "In contrast, leiomyosarcoma is negative for KIT mutations and mostly positive for desmin, SMA, h-caldesmon, and vimentin." (PMID 38993816, 2024). "Most cases reported in the “pre-KIT era” as leiomyosarcoma of the stomach might be GISTs." (PMID 34143361, 2021). "These tumors can differentiate from other subepithelial lesions, including leiomyoma, leiomyosarcoma, GI cysts, and lipoma; through IHC by the positiveness of CD117 and KIT negativeness of Desmin and S100." (PMID 35658308, 2022). "Kinase targets found in the analysis were for osteosarcoma (KIT), Ewing’s sarcoma (ALK), undifferentiated pleomorphic sarcoma (JAK2, ABL2), alveolar rhabdomyosarcoma (NTRK1), and leiomyosarcoma (ALK)." (PMID 29541442, 2018). "As with leiomyosarcoma, miR-152 is downregulated in UPS and negatively correlates with MET and KIT mRNA levels." (PMID 28895916, 2017). "The intracellular tyrosine kinase c-SRC pathway, including as downstream targets EGFR, PDGFR and c-KIT, has been reported to be up-regulated in STS, especially leiomyosarcoma and synovial sarcoma." (PMID 28571564, 2017). "Currently, the only targeted therapy approved in leiomyosarcoma patients is pazopanib, a multitargeted inhibitor blocking VEGFR, PDGFR, FGFR, and c-KIT." (PMID 26576131, 2015). "Nearly all are immunohistologically positive to CD117 (KIT tyrosine kinase) as in our case, which differentiates it from true leiomyomas, neurofibroma, leiomyosarcoma and schwannoma." (PMID 18045506, 2007). "From a histological perspective, both GISTs and leiomyosarcomas share similar features, so a definitive diagnosis relies on immunohistochemical data: a vast majority of GISTs express c-KIT protein (CD117) and CD34, whereas leiomyosarcomas often express desmin and smooth muscle actin." (PMID 37395913, 2023). "We present a case of a 43-year-old patient operated on for a primary mesenteric leiomyosarcoma with a positive immunostain for DOG1, despite having no KIT or PDGFRa mutations on molecular analysis." (PMID 35755504, 2022). "In leiomyosarcoma, miR-152 targets the tyrosine-protein kinases: MET and KIT." (PMID 28895916, 2017). "Histologically a GIST tumor is very similar to leiomyosarcoma (LMS) but in our case non c-KIT positivity was not checked and the tumor was originally diagnosed as uterine leiomyosarcoma." (PMID 19116036, 2008). "KIT immunostaining is an important method for diagnostic distinction of GIST from leiomyoma, leiomyosarcoma, and schwannomas, which typically do not exhibit KIT positivity." (PMID 18096058, 2007). "Specifically, most GISTs express KIT (CD 117, c-KIT), a highly sensitive and specific marker for GIST, while leiomyomas and leiomyosarcomas do not." (PMID 31730471, 2019). "Leiomyosarcoma tumor cells typically show positive staining for SMA, desmin, calponin, and h-caldesmon and negative staining for CK, S-100 protein, HMB-45, and CD117 (c-KIT)." (PMID 40755625, 2025). "Finally, we confirmed the expected overexpression of some genes: KIT and ANO1/DOG1 in GISTs, MDM2 and CDK4 in non-myxoid/round cells liposarcomas, CALD1 and tropomyosin genes (TPM1, TPM2) in leiomyosarcomas, PDGFB in DFSPs, MUC1/EMA in synovial sarcomas, and CD34 in SFTs." (PMID 23734203, 2013).
leiomyoma (58 papers, 2007 to 2025). A well-circumscribed benign smooth muscle neoplasm characterized by the presence of spindle cells with cigar-shaped nuclei, interlacing fascicles, and a whorled pattern. "Most IFPs express CD34 and lack markers such as CD117 (c-KIT) and S100, assisting in their differentiation from GISTs, leiomyomas, and neural tumors." (PMID 40636665, 2025). "Staining is also positive for CD117 (KIT oncogene and transmembrane tyrosine kinase) in over 95% of GISTs suggesting the same primitive mesenchymal cell origin thus differentiating these tumours from true leiomyomas." (PMID 23634309, 2013). "In leiomyomas, the neoplastic cells are negative for KIT, but KIT-positive mast cells and interstitial cells of Cajal (ICC) are often intermingled; this finding should not be confused with GIST." (PMID 38609732, 2024). "Inappropriately classified in the past as Leiomyomas, Leiomyoblastomas, and Schwannomas, in the late 1990s they were classified as a single neoplastic entity, when immunohistochemistry had identified the gene KIT (CD117)." (PMID 24455386, 2013). "Another diagnostic marker for GISTs, DOG1 (Discovered on GIST 1, also known as Anoctamin-1), shows even higher sensitivity, detecting up to 36% of KIT-negative GISTs, but it is commonly expressed in gastric carcinomas and mesenchymal sarcomas such as leiomyoma and synovial sarcoma." (PMID 35804982, 2022). "Immunohistochemical staining was positive for αSMA and desmin, negative for CD117 (KIT) and S100, and the patient was diagnosed with benign leiomyoma." (PMID 35620231, 2022). "The leiomyoma was immunohistochemically positive for vimentin, α-smooth muscle actin, and desmin (1 case), but negative for cytokeratins, CD34, KIT, and PDGFRA." (PMID 27956961, 2009). "Unlike GIST or leiomyoma, GCT is negative for KIT protein and Desmin." (PMID 34677732, 2022).
mast cell tumors (57 papers, 2007 to 2025). "For example, single gene-based assays have been available for years for diagnosing KIT mutations in mast cell tumors (MCTs), while assays for BRAF mutations in urothelial carcinomas have just been identified." (PMID 40616061, 2025). "KIT mutation status of a 12‐year‐old male domestic cat with multiple subcutaneous mast cell tumours." (PMID 39177283, 2024). "The RTK KIT protein is expressed in feline mast cell tumors in different locations, with cytoplasmic expression linked to a worse prognosis in the cutaneous form." (PMID 37835664, 2023). "A genetic relevance has been widely highlighted in canine mast cell tumors, in which KIT gene mutations are significantly associated with an increased incidence of recurrent disease and death and furthermore associated with an aberrant protein localization." (PMID 36139188, 2022). "Most canine mast cell tumors exhibit different mutations in the c-KIT gene, including internal tandem duplications in the juxtamembrane region, which result in the constitutive activation of KIT, leading to increased and uncontrolled cell proliferation." (PMID 35159380, 2022). "One of the mechanisms underlying the action of toceranib in mast cell tumor is the inactivation of the tyrosine kinase protein KIT that is expressed in neoplastic cells." (PMID 33827546, 2021). "Gain-of-function mutations in KIT are driver events of oncogenesis in mast cell tumours (MCTs) affecting companion animals." (PMID 32075643, 2020). "As an example of translational medicine, masitinib mesylate (AB1010) was initially approved in veterinary medicine for the treatment of unresectable canine mast cell tumors activated by KIT mutation." (PMID 29385676, 2018). "Mast cell tumors with c-KIT mutations treated with vinblastine and prednisone tended to have increased DFI (1 month vs. 6.5 months) and OS times (1 month vs. 8.9 months); however, these associations were not statistically significant." (PMID 18700956, 2008). "Recently, canine and human mast cell neoplasms were compared, and the importance of comparative oncology was highlighted: human systemic mastocytosis and canine mast cell tumors share many characteristics such as diagnostic approaches, c-KIT mutations, and even treatment modalities." (PMID 35159380, 2022). "However, apart from KIT, also other KIT-independent oncogenic molecules and triggers have been implicated in the development of mast cell tumors in mice." (PMID 21297223, 2010). "The reported canine c-KIT mutations have been associated with mast cell tumors as well as GISTs." (PMID 20950418, 2010). "For instance, the oncogenic KIT mutations, such as KIT D816V and KIT V560G, lead to constitutively active tyrosine kinase activity and growth factor-independent proliferation of mast cells in tissue lesions associated with mast cell tumors and systemic mastocytosis." (PMID 37041174, 2023). "On the other hand, toceranib phosphate, a tyrosine-kinase inhibitor, licensed for use in dogs, is primarily recommended for the treatment of canine mast cell tumors due to its inhibition of the receptor KIT." (PMID 39902337, 2024). "Our findings encourage further investigation into the development of therapeutic strategies for feline mast cell tumours, particularly focusing on the heterogeneous nature of KIT/KIT and overcoming acquired resistance to toceranib." (PMID 39177283, 2024). "KIT D816V is commonly observed in mast cell neoplasms, whereas T847M has been identified in four malignant neoplasms, including conjunctival melanoma." (PMID 39564955, 2024). "Toceranib (Palladia), the first FDA-approved first tyrosine kinase inhibitor for treating dogs with mast cell tumor, targets KIT, VEGFR, FLT3 and PDGFR." (PMID 38201229, 2023). "Recent research has focused on the receptor tyrosine kinase (RTK) KIT which is involved in the pathogenesis of canine mast cell tumors (MCT)." (PMID 36072760, 2022).